ELN (elastin)
Diseases named in the same sentence as ELN in open-access papers (continued):
Sharing a sentence is not in itself a finding about the gene and the disease.
Hypertension (continued). "Remodeling of vascular ECM in hypertension is manifested with collagen deposition and elastin fragmentation which alters the collagen-to-elastin ratio and results in arterial wall thickening, while the expression of proteoglycans and glycoproteins is also upregulated." (PMID 38177257, 2024). "Moreover, Isg15-null mice were found to be protected against angiotensin II-induced hypertension, elastin remodeling, vascular stiffness, endothelial dysfunction, and expression of inflammatory and oxidative stress markers." (PMID 37025175, 2023). "However, elastin fibers are prone to fragmentation, and their orderly arrangement gradually disappears in cases of arterial stiffness and hypertension." (PMID 36838830, 2023). "Hypertension also increases collagen fiber production and accelerates elastin fiber degradation." (PMID 38037153, 2023). "Hypertension can also increase the activity of matrix metalloproteinases (MMPs), a family of enzymes that break down extracellular matrix proteins, including collagen and elastin." (PMID 38037153, 2023). "The hypertension-related pathogenesis of CMBs involves the upregulation of matrix metalloproteinases, which degrade collagen, elastin, and other components of the basal lamina and extracellular matrix, thus destroying the structural integrity of the cerebral vessels." (PMID 36726156, 2023). "Previously, we used a murine model of elastin haploinsufficiency (Eln+/− mice) to demonstrate that elastin insufficiency alters the structure and function of the renal microvasculature and that these changes precede the development of hypertension." (PMID 37179824, 2023). "First, although the murine AAA model of Ang II infusion in ApoE−/− C57BL/6 mice simultaneously receiving HFD for 28 days has been reported to mimic hypertension and hyperlipidemia of clinical AAA patients, there are other risk factors such as elastin degradation in AAA pathophysiological changes." (PMID 35883151, 2022). "Lower amounts of collagen and elastin in aortas of patients with hypertension were also shown." (PMID 33006035, 2021). "Fibrillin-1 is an extracellular matrix protein with load-bearing and anchoring functions in the arterial wall, directing the orientation of elastin fibers associated with aortic and arterial stiffness; FBN1 genotypes may thus contribute to hypertension." (PMID 33807627, 2021). "Arterial hypertension may further alter the elastin–contractile unit proper function, leading to SMC apoptosis, to increased production of matrix metalloproteinases, proteoglycans and TAA." (PMID 33807627, 2021). "These murine and clinical models suggested that the absence of elastin and therefore of functional elastic fibers was the cause of hypertension in these individuals." (PMID 34782679, 2021). "While our study was focused on elastin, both collagen and elastin cross-linking could contribute to vascular stiffness in hypertension as has been suggested in Ang II-infused animals." (PMID 31615160, 2019). "The levels of the two elastin degradation markers neither showed significant correlation with troponin I levels nor did they correlate with the risk factors of hypertension, diabetes and hypercholesteremia." (PMID 23805173, 2013). "The effect of L-NAME-induced hypertension was not prevented by piperine alone, but curcumin with or without piperine caused an increase of elastin proportional content reaching the level of controls when combined with piperine." (PMID 22005253, 2011). "For example aging and hypertension may contribute to an overproduction of collagen and breaks in elastin fibers." (PMID 21122147, 2010). "First, MPM imaging of aortic collagen and elastin fibres was performed on spontaneously hypertensive rats and Wistar–Kyoto controls across three critical age stages (prehypertension, developing hypertension and stable hypertension) and two aortic segments (abdominal aorta and thoracic aorta)." (PMID 40904990, 2025).
Hypertension (continued). "In addition, in these elastin-deficient mice, vascular stiffening is detectable seven days after birth, but hypertension does not manifest until around the 14th day." (PMID 40001457, 2025). "Elastin synthesis in arterial walls occurs at the end of gestation, and a shorter gestation can disrupt this process and cause elastin disruption, which in turn increases vascular stiffness, leading to an increase in SBP and ultimately greater risk of hypertension." (PMID 39895512, 2025). "In individuals with hypertension, it is found lower arterial compliance as well as higher arteria wall viscosity, which can be attributed to altered arterial and blood flow pressures due to increases in wall thickening, collagen deposition, or elastin fragmentation." (PMID 40892713, 2025). "Additionally, hypertension can also accelerate the degradation of elastin fibers." (PMID 38037153, 2023). "Because elastin is a main structural element of arteries and is a potential target for the formation of AGEs, we investigated serum levels of IgM and IgG autoantibodies to AGEs of vascular EL (AGE EL) in patients with advanced T2D and hypertension, who are at increased cardiovascular risk." (PMID 35997390, 2022). "Vessel remodeling involving elastin fiber fragmentation and reduced axial stretch lead to high prevalence of vessel tortuosity in hypertensive patients, and numerous studies suggest vessel tortuosity as an indicator of arterial hypertension, stroke and ischemic heart disease." (PMID 35789256, 2022). "A 2-week infusion of angiotensin II to induce hypertension in Wistar rats also resulted in a reduced number of fenestrae and a reduction in the total fenestrae area in the mesenteric vasculature and this coincided with an increase in the relative area occupied by elastin." (PMID 27458385, 2016). "The absolute amount of elastin in the aortic media, however, was increased when compared to control, which could be ascribed to the increased synthetic activity of vascular wall cells as a response to the increased fatigue of elastin depicted also in other models of experimental hypertension." (PMID 22005253, 2011). "Clearly, our histological analysis revealed marked collagen accumulation in the medial and total vessel wall, in addition to elastin degradation and fragmentation, consistent with the ECM remodeling characteristics of hypertension." (PMID 41295367, 2025). "Given the central role of LOX in collagen and elastin cross-linking, we have recently assessed the contribution of LOX to vascular stiffness and hypertension." (PMID 31615160, 2019). "Animals with hypertension had increased wall thickness and cross-sectional area of the aorta, accompanied by relative increase of PTAH positive myofibrils and decrease of elastin, collagen and actin content." (PMID 22005253, 2011). "Interestingly, reports on elastin remain variable: some studies show increased elastin in SHR and other hypertension models as a compensatory mechanism, while others report reduced elastin or fragmentation." (PMID 41295367, 2025). "Meanwhile, both our previous research and the data from the present study suggest that HU and hypertension induce a switch to a synthetic phenotype in VSMCs, characterized by increased expression of OPN and elastin, along with decreased levels of α‐SMA and SMMHC." (PMID 40622073, 2025). "Animal studies have shown that increased arterial stiffness, leading to hypertension-induced vascular changes and ICH, may be attributed to the dysregulation of matrix metalloproteinases (MMPs), elastin, and collagen." (PMID 40994710, 2025). "Our study suggests that this may occur through a mechanism involving the induction of hypertension by oral axitinib, as well as MMP-9 degradation and the intravenous pembrolizumab destruction of elastin and collagen in the aortic wall." (PMID 38887778, 2024).
Hypertension (continued). "Moreover, in established hypertension, YAP/TAZ knockout results in severe vascular lesions in small mesenteric arteries characterized by neointimal hyperplasia, elastin degradation, and adventitial thickening." (PMID 35196875, 2022). "In this report, based on in vitro data suggesting a vasocontractile role for AT2R in elastin insufficiency, we sought to determine whether AT2R contributes to elastin insufficiency-mediated hypertension in vivo." (PMID 34790711, 2021). "If insufficient elastin synthesis leads to vascular complications and arterial hypertension in children with WBS, restoration of sufficient quantity of elastin should then result in prevention or inhibition of arterial stenosis and improvement in arterial blood pressure." (PMID 31138170, 2019). "The main functional consequence is an increase in vascular tone and an alteration of endothelium-dependent relaxation, leading to an increase in carotid stiffness in adult Vim−/− mice, in the absence of hypertension and changes in the elastin/collagen ratio." (PMID 28912461, 2017). "As reviewed above, an increase in vascular stiffness can be observed in hypertension in in the absence of increased collagen content and decreased elastin content as the literature on this point is not consistent." (PMID 26635621, 2015). "Since the three primary constituents – collagen, smooth muscle, and elastin – did not change at 4 weeks of hypertension in the MCA, this increase in thickness would have been due to other cells or ground substance matrix." (PMID 23162468, 2012). "L-NAME-induced hypertension leads to an increase of the aortic media thickness and its cross-sectional area, which are accompanied by the increased proportional amount of PTAH-positive myofibrils, decrease of elastin, collagen and actin." (PMID 22005253, 2011). "This sexual dimorphism in vascular adaptation appears to serve as a compensatory mechanism preventing hypertension development, with the differential accumulation of collagen and elastin in female offspring conferring a protective effect absent in male counterparts." (PMID 40443735, 2025). "Increased collagen content and destruction of the elastin fiber network together with a proinflammatory microenvironment contribute to ECM remodelling and increased intima-media thickening and vascular stiffness in small and large arteries in human and experimental hypertension." (PMID 27118293, 2016). "Additionally, hypertension also leads to vascular remodeling, which involves changes to the vascular smooth muscle cell (VSMC) of both large and small arteries, and other cellular components of the vascular wall, including endothelial cells, elastin, and collagen content." (PMID 39907407, 2025). "However, an in depth analysis of published studies of hypertension strongly suggest that this view of an increased collagen to elastin ratio may not be entirely accurate." (PMID 26635621, 2015).
aortic aneurysm (65 papers, 2006 to 2026). A ruptured aneurysm located in the wall of the proximal portion of the descending aorta proceeding from the arch of the aorta. "Polymorphisms in the ELN gene are known to contribute to the pathogenesis of aortic aneurysms and arterial dilatations." (PMID 40259928, 2025). "During an aortic aneurysm, matrix metalloproteinases (MMPs) degrade elastin, causing the aortic wall to dilate permanently." (PMID 39252788, 2024). "Defects in the components of those pathways [Collagen Type IV Alpha 2 Chain (COL4A2), Collagen Type IV Alpha 1 Chain (COL4A1), Collagen Type VI Alpha 1 Chain (COL6A), Elastin (ELN)] were previously proposed to be associated with aortic aneurysm formation." (PMID 36922793, 2023). "Aortic aneurysms (AAs) consist of slow proteolysis and loss of both collagen and elastin matrix in the aorta wall, leading to wall dilation, weakening and rupture in well-advanced lesions." (PMID 26110102, 2015). "Accordingly, this review investigated whether plasma desmosine (pDES), a highly specific marker of elastin degradation, could be used as a non-invasive biomarker for detecting aortic aneurysms and assessing their risk profile." (PMID 41976840, 2026). "Interestingly, aortic aneurysm and insufficiencies of cardiac valves characteristic for connective tissue disorders have also been reported in patients with ELN variants." (PMID 41010011, 2025). "The results showed that the protective effect of LEN was totally abolished by SLC44A2 deficiency, as evidenced by unimproved aortic aneurysm incidence, aortic diameter expansion, aortic rupture rate, elastin breakage, and MMP activation in Ang II–infused Slc44a2SMKO mice treated with LEN." (PMID 38916960, 2024). "Thus, it was previously thought that genes which encoded proteins involved in the structure or function of the vascular smooth muscle cells (VSMC) elastin-contractile unit were altered to cause aortic aneurysms and dissection." (PMID 39054468, 2024). "As in aortic aneurysms, localized changes in shear stress may signal underlying elastin degradation." (PMID 35224059, 2022). "Similarly, ELN variants associated with aortic aneurysms could transform surveillance strategies for aortopathies." (PMID 41172738, 2025). "Other mechanisms, such as epigenetic regulation and chemical modification of matrix components especially elastin fibers, have been implicated in the detrimental effects of nicotine on tissue homeostasis and might be applicable in the context of aortic aneurysm formation." (PMID 34646889, 2021). "Histopathological analysis demonstrated that AngII+HS induced elastin degradation and collagen deposition, reproducing the pathological features of human aortic aneurysm." (PMID 41041074, 2025). "Rupture, fragmentation of elastin fibers, and disordered collagen deposition are histological changes found in the architecture of the arterial wall in aortic aneurysms." (PMID 40521351, 2025). "For instance, the use of elastin-targeting nanoparticles to deliver matrix-stabilizing agents has shown success in aortic aneurysm models." (PMID 39595942, 2024). "Consistent with this, patients with mutations in fibulin‐4 suffer from cardiovascular complications, including aortic aneurysms, arterial tortuosity, and elastin abnormalities as described in detail previously." (PMID 38853023, 2024). "Elastica van Gieson (EVG) staining revealed strong and uniform elastin laminae in control samples, whereas disorganized elastin laminae with increased fragmentation (characteristic of aortic aneurysms) were prominent in samples from patients with sporadic TAA." (PMID 37394473, 2023). "Tissue characterization of the aneurysm sites reveals severe media deterioration, elastin breakdown, immune cell infiltration, and lipid accumulation — features closely reminiscent of advanced human aortic aneurysm." (PMID 36625347, 2023).
aortic aneurysm (continued). "Aortic aneurysms were characterized by elastin disarray, SMC apoptosis, and accumulation of proteoglycans and immune cell populations." (PMID 37561588, 2023). "The studies reveal classical histological features of aortic aneurysm, including atheroma, lymphocytic infiltration, elastin disruption, and myxoid degeneration with probable AS association." (PMID 37828432, 2023). "In line with humans, mice Ang II-induced aortic aneurysm displayed remarkable elastin break and reduction of number of SMCs." (PMID 36703732, 2022). "Mechanistic research report that smoking promotes the degradation of collagen and elastin and consequent weakening of the arterial wall by highly expressed matrix metalloproteinase in aortic wall, finally leading to aortic aneurysm formation." (PMID 35120453, 2022). "Earlier studies have extensively described that aortic aneurysms show fragmentation of elastin fibers indicating media degeneration." (PMID 35137689, 2022). "In contrast, blinded quantitative assessment of elastin amount and medial cell number distinguished aortic aneurysms and referent specimens, albeit with marked overlap in results." (PMID 34162971, 2021). "Histological analysis of the aortic aneurysm tissues revealed that angiotensin II-infused CTLA-4-Tg/Apoe−/− mice had more preserved elastin content compared with control mice." (PMID 31147569, 2019). "Nevertheless, it is of interest that increased synthesis of matrix molecules, including elastin accompanies aortic aneurysms, probably as a compensatory mechanism." (PMID 29470511, 2018). "Similar to Marfan syndrome, mutations in both TGFBR1 and TGFBR2 result in disruption of collagen and elastin fiber biology in the vessel wall and aortic aneurysm formation." (PMID 28116311, 2017). "Inflammation and degradation of elastin fiber networks by MMPs are known to play a crucial role in the formation of aortic aneurysms in patients with MFS and the mgR/mgR Marfan mouse model." (PMID 26840980, 2016). "Although pathological features of aortic aneurysms varied with different positions (ie, thoracic or abdominal aorta), the degradation of elastin was their common characteristics." (PMID 25243605, 2014). "We previously reported that intra-abdominal implantation of BM-MSCs sheets by laparotomy inhibited the development of Ang II-induced aortic aneurysm in apoE−/− mice by anti-inflammation and elastin preservation." (PMID 23875706, 2013). "Studies of aortic aneurysms have already shown a significant reduction of elastin content in the diseased aortic wall, which probably occurs due to a high elastase activity." (PMID 16824202, 2006). "Third, in mice, IH was demonstrated to increase vascular cell production of matrix metalloproteinases (MMPs) and metalloproteinases, including ADAM‐17 and the elastases MMP2 and MMP9, resulting in alteration of elastin in the aortic wall and the development of aortic aneurysms." (PMID 41541542, 2026). "Inflammation, genetic deformities, apoptosis, biomechanical wall stress, and proteolytic degradation of connective tissue including elastin and collagen may lead to the development of an aortic aneurysm." (PMID 36195877, 2022). "Furthermore, BMSCs have been established to significantly attenuate aortic elastin degradation and aortic aneurysm development as well as reduce IL-1β." (PMID 33460398, 2021). "Since elastin is considered an important biomarker in the progression of aortic aneurysms, spatially designed nanoparticles targeting the elastin protein could facilitate a new dimension to current knowledge of diagnosis and therapy of AAAs." (PMID 33799932, 2021). "In human the length of the suprarenal but infradiaphragm is consistent and mainly called as superior abdominal aorta or suprarenal aorta; however a reduced vasa-vasorum, high incidence of aortic aneurysms, and reduced elastin level are described specifically for the infrarenal aorta." (PMID 31016040, 2019).